APC (APC regulator of Wnt signaling pathway)
Diseases named in the same sentence as APC in open-access papers (continued):
Sharing a sentence is not in itself a finding about the gene and the disease.
tumor (continued). "In this study, we found that niclosamide activates nuclear YAP activity with inactivation of the tumor-suppressive Hippo pathway in APC-mutated CRC cells." (PMID 34298652, 2021). "Further, increased APC co-inhibition, along with the increase of MRGs based risk score, partly reflects the defected neoantigen recognition, presentation, and anti tumor effects." (PMID 33747931, 2021). "Our lab has previously shown that APC loss-of-function results in increased tumor initiating cells (TICs)." (PMID 34370741, 2021). "Considering the genetic profile of our patient’s tumor, the results of immunohistochemical staining were also consistent with loss of APC function, driving pathologic nuclear beta-catenin activity." (PMID 34549183, 2021). "In the MCCS, higher tumour methylation showed association with shorter overall survival for APC (HR = 1.28, 95% CI: 1.07–1.53), HIST3H2A/HIST3H2BB (HR = 1.28, 95% CI: 1.02–1.62), CELF2 (HR = 1.30, 95% CI: 1.07–1.58) and TMEM101 (HR = 1.21, 95% CI: 1.00–1.48)." (PMID 33461604, 2021). "Other studies have shown that overexpression of PPM1D together with oncogenes augmented tumor formation in mice or resulted in reduced the survival of mice deficient of the APC tumor-suppressor gene." (PMID 34771656, 2021). "APC acts as a protein of tumor inhibition, which encodes an antagonist responding to Wnt signaling pathway." (PMID 34681938, 2021). "We also carried out a xenograft assay using APC-overexpressed Hep3B and Huh1 cells to investigate the association between EHMT2 and APC in tumor growth in vivo." (PMID 34344448, 2021). "A high abundance of the bacteria of Bacillus genus has been found in tumors positive for APC mutations, while the bacteria of Ruminococcus genus was dominant in tumor positive for KMT2C mutation." (PMID 33807878, 2021). "In the series of 27 tumor/germline matched analyses, 4 cases harbored protein-truncating APC mutations and indeed all were observed only in the tumor sample." (PMID 33500480, 2021). "The EGFR inhibitor erlotinib exhibits tumor-preventive efficacy in individuals with familial adenomatous polyposis, a syndrome caused by inheritance of a mutant allele of APC." (PMID 34513688, 2021). "Both the volume and weight of tumours were significantly decreased in APC-mutated CRC cells stably expressing PKM2 shRNA compared with those of APC-mutated CRC cells containing control shRNA." (PMID 33071283, 2021). "For example, loss of adenomatous polyposis coli (APC) gene in CRCs results in the deterioration of the intestinal barrier, and the subsequent microbial invasion into the tumor bed triggers inflammatory responses, thereby promoting tumor growth." (PMID 34063828, 2021). "The median CCF value of APC was the highest in both primary tumor and metastases, indicating that APC mutation was involved in liver metastasis in addition to tumorigenesis." (PMID 34453042, 2021). "In this context, MYD88 has also been shown to play an integral role in spontaneous tumour development in mice with a mutation in the adenomatous polyposis coli (APC) gene and in carcinogen-induced colon tumour development." (PMID 33597599, 2021).
tumor (continued). "POLE, BLM, ARID1A and APC genes were mutated within a tumor that originated within the temporal lobe, but for this gene the highest expression was in the midline structures as opposed to temporal lobe." (PMID 34257334, 2021). "The APCMin/+ (multiple intestinal neoplasia) mouse model harbors a germline mutation in the APC tumor suppressor gene and exhibits multiple tumors in the small intestine and colon; the downregulation of miR-194 promoted tumor formation in APCMin/+ mice." (PMID 34062897, 2021). "Studies have demonstrated that superoxide production by RAC1-dependent NADPH oxidase is critical for WNT signaling and necessary for tumor formation after APC loss." (PMID 33557356, 2021). "Overall, these results showed that increased glycolytic enzyme expression and tumour growth due to APC loss were diminished by inhibition of Wnt/β-catenin signalling in vivo." (PMID 33071283, 2021). "Many studies of genetically modified APC-deficient mouse strains demonstrated that APC is crucial in colon, skin, breast, thymus, and nervous system development, as well as neoplasia production." (PMID 32586050, 2020). "APC is a tumour suppressor gene which encodes the adenomatous polyposis coli (APC) protein, with a known role in the cellular processes of tumourigenesis." (PMID 33076494, 2020). "The C-terminus of APC binds MTs, and truncations of APC in cancer suggest a loss of APC–MT interactions and a decreased MT stability, which promote tumor development." (PMID 33105836, 2020). "Another deubiquitinase USP7 serves as a tumor-specific Wnt activator in APC-mutated CRC by promoting β-catenin deubiquitination." (PMID 33291655, 2020). "FAP patients develop 100s to 1000s of premalignant adenomas which further supports the idea that APC mutations drive tumor growth in vivo." (PMID 33112876, 2020). "Researchers found that higher methylation values of four genes (RASSF1A, CDH1, CDH13, and APC) were significantly associated with several traits of poorer outcome (tumor stage, growth pattern, muscle invasion, and tumor grade)." (PMID 33092083, 2020). "APC loss of function is a key event in the colon carcinogenesis and represents the first event in the tumor initiation." (PMID 33066148, 2020). "Based on the enrichment results of KEGG pathway, we noticed a familiar tumor suppressor gene, APC, which is associated with several carcinoma related pathways: Hippo signaling pathway, MAPK signaling pathway, and pluripotency of stem cells." (PMID 33363011, 2020). "Six of those cases with a germline APC variant were shown to harbor one additional somatic APC variant or per tumor nodule a distinct variant or LOH." (PMID 31598872, 2020). "It turns out that two variant-associated genes KRAS and APC exist in five out of seven primary tumor samples and six out of seven primary tumor samples, respectively." (PMID 32901013, 2020). "In this study we found a higher than anticipated rate of APC gene mutation in a cohort of EOCRC tumours, with sporadic mutations occurring throughout the gene rather than clustering in one region as expected." (PMID 33352971, 2020). "Gene APC, which is involved in Wnt/β-catenin signaling pathway, has been reported to be associated with tumorigenesis, tumor metastasis and resistance." (PMID 33425983, 2020). "The aim was to segregate tumours into two clusters: LI tumours with identifiable mutations in APC or CTNNB1 and LD lesions with RSPO2/3 fusions or RNF43 alterations." (PMID 31563876, 2020). "For example, ApcMin/+ mice, a familial model of colonic tumor disease, spontaneously developed intestinal tumors due to a mutation in the adenomatous polyposis coli (APC) tumor-suppressor gene." (PMID 33329610, 2020).
tumor (continued). "In contrast, the constitutive, intracellular activation of Wnt signalling through APC or CTNNB1 mutation in LI tumours, renders upstream Wnt NRs functionally redundant and uncouples appropriate feedback loop equilibrium." (PMID 31563876, 2020). "Loss of the autophagy-related gene Atg7 in intestinal epithelial cells was shown to attenuate tumor growth driven by loss of adenomatous polyposis coli (APC), a major tumor suppressor in colorectal cancer." (PMID 33381037, 2020). "One case with a germline APC variant harbored two concurrent somatic CTNNB1 variants at a different tumor site each." (PMID 31598872, 2020). "The tumour without an RNF43 mutation harboured two truncal mutations in the APC tumour suppressor gene as an alternative mechanism of β-catenin activation." (PMID 31949146, 2020). "There are several mutations that can cause an accumulation of β-Catenin in tumor cells such as mutations of the APC gene, point mutations in GSK-3β or mutations in β-Catenin gene itself." (PMID 32811441, 2020). "This suggests that the tumorigenic effects of fusobacteria operate downstream of the loss of the APC tumor suppressor and the consequent intestinal dysplasia that occurs in ApcMin/+ mice." (PMID 33013813, 2020). "It is possible that the addition of a truncating APC mutation in this context is disadvantageous to tumor progression." (PMID 32384699, 2020). "In fact, APC min mice with a single allele inactivation of EphB4 showed shorter lifespan, larger tumor size in the small intestine and more abundant tumors in the large intestine." (PMID 32316101, 2020). "This initial event was associated with hyperactivation of the Wnt/β-catenin pathway and loss of function of the APC tumor suppressor." (PMID 32708919, 2020). "The loss of APC and subsequent Wnt signaling support macrophage infiltration into the tumor, which negatively impacts the drug response." (PMID 33105836, 2020). "Significantly, 85% of CRC cancers are associated with mutations in the APC gene, resulting in a loss of its tumor suppressor function." (PMID 33105843, 2020). "The location of these truncating APC mutations affects the properties of the resultant protein and the tumour phenotype." (PMID 33352971, 2020). "Our finding that APC mutations in EOCRC more closely resembled the pattern of APC mutations seen in FAP fits with the observation that EOCRC tumours are predominantly distal." (PMID 33352971, 2020). "Inactivating mutations of APC leads to constitutive activation of Wnt/β-catenin signaling and tumor development." (PMID 33276489, 2020). "Although DCC-deficient mice (like MET D1374N mice, data not shown) do not develop spontaneous tumors, experiments in which they were crossed with mice bearing a cancer-predisposing APC mutation suggest that DCC acts as a conditional tumor suppressor gene." (PMID 32091387, 2020). "Further, in FAP and sporadic CRC patients, mutation in the adenomatous polyposis coli (APC) gene increases autocatalytic tissue polymerization and induces tumor tissues to autocatalyze their own progressive growth, which drives tumor development in the colon." (PMID 32079164, 2020). "(iv) The extent of APC mutation (most mutations lead to truncation of the protein product) correlates with the severity of the tumor." (PMID 33112876, 2020). "Strikingly, tumor models driven by APC loss correlate with CMS2/3, which confers better disease prognosis." (PMID 31526760, 2019). "Our results suggest a role for Wnt signaling biology in this tumor, as we found elevated proteins associated with Wnt biology, enrichment of APC mutations, and the presence of an oncogenic mutation in CTNNB1." (PMID 31395880, 2019).
tumor (continued). "The second tumour suppressor gene product of the canonical Wnt/β-catenin pathway to be associated with SCZ is adenomatous polyposis coli (APC)." (PMID 30809121, 2019). "Validated variants showed that the tumor suppressor genes APC and ARID1 and the DNA MMR genes MSH3 and MSH6 are the genes with the highest numbers of validated variants." (PMID 31080553, 2019). "To understand the relative dependencies of β-catenin mutant and APC-deficient tumours on BCL9/9l, we examined the intracellular distribution of β-catenin." (PMID 30760720, 2019). "Because of frequent random inactivation of the second APC allele and successive accumulation of additional tumor-promoting mutations, the polyps progress to carcinoma by the age of 35." (PMID 31614493, 2019). "NGS analysis of both tumor and blood samples in one patient revealed the presence of mutation in the APC gene, with homozygous deletion in tumor cells." (PMID 30523493, 2019). "Detected variant was present in heterozygous state in patient’s leukocytes in contrast to tumor DNA where homozygous deletion leading to inactivation of both copies (loss of heterozygosity) of APC gene was observed." (PMID 30523493, 2019). "This APC mutation was found in 7 out of the 9 patients analyzed, which confirmed the tumor origin of the cells isolated by the CROSS chip." (PMID 31142796, 2019). "CIN occurs more frequently in tumour showing APC and KRAS mutations, whereas the microsatellite instability phenotype is mainly associated with BRAF mutations." (PMID 31414579, 2019). "Mutations in APC occur in all CMS tumor groups, with the highest representation in CMS2 (83%) and the lowest in CMS1 (40%)." (PMID 31614493, 2019). "The potent and selective RNAi-mediated reduction in β-catenin levels by DCR-BCAT in preclinical models resulted in anti-tumor efficacy in tumors with both APC and other Wnt/β-catenin pathway mutations." (PMID 30800717, 2019). "Here we examine the requirement of BCL9/9l, constituents of the Wnt-enhanceosome, for intestinal transformation following loss of the tumour suppressor APC." (PMID 30760720, 2019). "Canonical WNT signaling is a central driver of cell proliferation, and both COLO320DM and HCT-15 cells display increased canonical WNT activity due to mutations in the APC tumor suppressor gene." (PMID 30717152, 2019). "We also analyzed the common downregulated genes and found that many of these genes such as ANKRD12, KIAA1551, and APC encode proteins with tumor suppressive functions." (PMID 30993034, 2019). "A low-frequency APC mutation in tumor OT281, represented by only 3% of sequencing reads, was retrieved as a homozygous mutation in the corresponding organoid culture." (PMID 30925167, 2019). "This distinctive synthetic lethality circuit created by APC inactivation in CRC strongly supports the intestine-specific tumor-suppressive effect of EEF2K and its association with better prognosis in CRC patients." (PMID 31266475, 2019).
tumor (continued). "In CRCs and other neoplastic diseases with a de-regulated Wnt pathway, inhibitory proteins other than APC are affected by mutation or modification." (PMID 31003440, 2019). "mTORC1 has been shown to play a role in cell proliferation and tumor growth in transgenic animals carrying APC mutations similar to what is seen in desmoid tumor patients." (PMID 29330550, 2018). "Spontaneous mutations inactivating the tumor suppressor, APC, or stabilizing oncogenic β-catenin represent the most common (>80%) driving mutations of sporadic colon cancer." (PMID 30131940, 2018). "Both tumours with APC mutation and all six tumours harbouring β-Catenin missense mutations showed expression of active β-Catenin at varied levels." (PMID 29872083, 2018). "The study of tumor organoids allowed the better definition of the role of WNT hyperactivation induced by APC loss on the perturbation of normal intestinal stem cell homeostasis." (PMID 29652830, 2018). "Both CTNNB1 wild-type tumours showed a copy neutral loss of heterozygosity within chromosome 5q (APC) and we identified APC frameshift deletions (E1309fs ΔAAAAG and Q1062fs ΔACAAA)." (PMID 30392813, 2018). "APC is a prototypical tumor suppressor, where an initial spontaneous mutation produces allelic heterozygosity and cancer susceptibility." (PMID 30131940, 2018). "The effectiveness and potential application of this compound in patients are demonstrated by the reduction in these proteins and the suppression of growth in tumor organoids derived from CRC patient tissues harboring both APC and KRAS mutations." (PMID 30459318, 2018). "This constitutive activity is mostly due to mutations of the APC tumor suppressor that result in the accumulation of β-catenin in the nucleus where β-catenin interacts with TCFs transcription factors to activate the transcription of target genes like c-myc." (PMID 30364258, 2018). "These limitations were related to the location of tumor development (mainly the small intestine) of traditional mouse models harboring APC mutations/deletions and to the overall tumor burden, limiting the time necessary for malignant progression." (PMID 29652830, 2018). "Mutations in components of the destruction complex (e.g. APC, β-catenin, Axin) are associated with increased nuclear accumulation of β-catenin and enhanced Wnt/β-catenin signaling in tumor cells." (PMID 29330435, 2018). "In this model, mutations in the adenomatous polyposis coli (APC) gene have been regarded as the earliest and the rate-limiting events of tumour initiation." (PMID 29872037, 2018). "As mentioned repeatedly above, APC loss of function is a key event in colon carcinogenesis, representing the first event in tumor initiation." (PMID 29652830, 2018). "Adenomatous polyposis coli (APC) or β-catenin gene mutations lead to increased tumor incidence through the stabilization of β-catenin and transcriptional activation with TCF-4, which play a pivotal role in CRC." (PMID 29464031, 2018). "To test the potential application of KYA1797K in humans, we established tumor organoids derived from CRC patient tissues harboring both APC (truncated form, Arg216*stop) and KRAS (Gly12Ser) mutations, which were identified by whole exome sequencing." (PMID 30459318, 2018). "KYA1797K suppressed the growth of tumor xenografts induced by CRC cells as well as tumor organoids derived from CRC patients having both APC and KRAS mutations." (PMID 30459318, 2018).